RET (ret proto-oncogene)
Diseases named in the same sentence as RET in open-access papers (continued):
Sharing a sentence is not in itself a finding about the gene and the disease.
thyroid cancer (continued). "Intriguingly, while driver gene fusions (RET fusions or NTRK fusions in PTCs, PAX8-PPARγ fusions in FTCs) are often mutually exclusive with driver gene mutations in well-differentiated thyroid cancer, they are generally absent in ATCs." (PMID 34944959, 2021). "Somatic molecular alterations typical of conventional (not hereditary) thyroid cancer such as RET/PTC rearrangements have been reported in some familial cases of C-MV of TC." (PMID 33495912, 2021). "Several MKIs inhibitors, that have been investigated in the treatment of RET-rearranged NSCLC, are approved for the treatment of thyroid cancers (i.e., vandetanib, cabozantinib, lenvatinib and sorafenib) or are approved for other indications (i.e., ponatinib, alectinib and sunitinib)." (PMID 33806299, 2021). "FTC (follicular thyroid carcinoma), the other major type of differentiated thyroid cancer, is generally negative for RET fusions." (PMID 32326537, 2020). "In recent NGS analyses of thyroid cancers, including ATCs, RET gene fusions were identified in more well-differentiated thyroid cancers, but were absent from ATCs." (PMID 32292131, 2020). "No data are now available on the potential role of RET as a tumor suppressor gene in thyroid carcinomas and the phenomenon of its deletion is not easy to be explained." (PMID 33383911, 2020). "RET kinase fusions have been recurrently detected in NSCLC and thyroid cancers." (PMID 29455648, 2018). "The correlations between ganetespib sensitivity and decreases in CDK1 levels, or decreases in phosphorylated or total levels of ERK1/2, AKT, 4E-BP1, S6 ribosomal protein and RET in eight thyroid cancer cell lines were not specifically evaluated in this study." (PMID 28476040, 2017). "Because PTC is the most common thyroid carcinoma, we included BRAF and RET/PTC in our research." (PMID 27654865, 2016). "High expression levels of FOXA1 and FOXA2 were also evident in a RET-mutant MTC cell line (TT) but not in established lines from other types of thyroid carcinoma." (PMID 26395490, 2015). "Notably, thyroid cancers have the highest frequency of recurrent kinase fusions (63/498, 13%), and all fusion events including ALK, BRAF, MET, NTRK1, NTRK2, RAF1 and RET are mutually exclusive in this cancer type." (PMID 25204415, 2014). "The encouraging results obtained by these drugs in non RAI-responsive differentiated thyroid carcinomas in some clinical trials where the RET rearrangement was not evaluated, were more likely due to the effects on neo-angiogenesis." (PMID 24267151, 2013). "Furthermore, previous data report other possible mechanisms of PI3K activation in thyroid carcinomas, such as the overexpression of RAI (ShcC/N-Shc), which is a substrate of RET oncoproteins." (PMID 23509459, 2013). "Further, our studies revealed expression of XB130 in human thyroid tissue, and we found that XB130 is a downstream mediator of the signaling cascade propagated by RET/PTC, a genetically rearranged, constitutively active, thyroid cancer-specific tyrosine kinase." (PMID 21884627, 2011). "Constitutive activation of RET, RAS, and BRAF which are principle initiators of thyroid cancer." (PMID 22654559, 2011). "The fusion oncoprotein RET/PTC3 (also known as RP3, indicating mouse/human gene or protein) is the most frequent isoform that develops in childhood thyroid cancers, and involves the partnering of the c-RET kinase domain with the androgen receptor-related protein RFG/ARA70." (PMID 18304343, 2008). "In recent years, several groups have demonstrated activation of the RET/PTC oncogene in the thyroids of humans with autoimmune thyroiditis without thyroid cancer." (PMID 18304343, 2008). "Whether the activity of Sorafenib in thyroid cancer is mediated by inhibiting RAF kinases, RET or its other targets is uncertain." (PMID 17179987, 2007).
thyroid cancer (continued). "In conclusion, our study has identified unique pathological characteristics associated with the RET and NTRK3 fusion genes in thyroid carcinoma cases, such as non-papillary structures, compressed nuclei, dysmorphic clear cells, calcification, and similarities with DSVPTC." (PMID 38472412, 2024). "Combination therapies exploring simultaneous inhibition of RET and the related pathways will provide insight into the clinical utility of such strategies, indeed several investigators have already started trials of combined therapy for patients with advanced MTC as well as other thyroid cancers." (PMID 36980956, 2023). "Finally, emerging therapeutic strategies for targeting RET are reviewed, with a particular interest in ongoing clinical trials emphasizing the expansion of access to highly selective RET inhibitors beyond NSCLC and thyroid cancers." (PMID 36918928, 2023). "Additionally, BRAF fusions and RET fusions were found in both cohorts, and activation of epithelial to mesenchymal transition (EMT) was also shown in both transcriptomes, all of which are typical features of thyroid cancer." (PMID 36941725, 2023). "The landmark 2022 US FDA regulatory approval of selpercatinib, a RET selective tyrosine kinase inhibitor (TKI), represented the seventh tissue-agnostic indication in oncology, following tumor site-specific approvals of selpercatinib for non-small cell lung cancer (NSCLC) and thyroid cancer." (PMID 37627175, 2023). "Molecular analysis in early childhood thyroid cancer cases demonstrated a very high prevalence of genome-wide rearrangements between the RET gene and the PTC3 and PTC1 genes, all located on the same chromosome 10, producing the RET/PTC3 or RET/PTC1 rearrangements." (PMID 35692388, 2022). "For RET fusion positive thyroid cancer, progression of the disease was not required." (PMID 35422765, 2022). "Transgenic overexpression of RET/PTC1 is indeed oncogenic and induces spontaneous and metastatic murine thyroid carcinomas that are histologically similar to human PTC tumors, though whether RET/PTC1 overexpression is an initiating factor in human thyroid carcinogenesis remained unclear." (PMID 35957881, 2022). "Additionally, in the thyroid cancer dataset, copy number analysis of the RET gene revealed decreases in 5 of the 46 samples, while no sample exhibited an increase in the RET copy number." (PMID 28178311, 2017). "The Authors used several thyroid cancer cell lines, but not MTC, so the effect on the cell cycle in the TT line might be linked to the specific inhibition of the mutated RET protein." (PMID 26081844, 2015). "Rearrangement of the RET tyrosine-kinase receptor with different genes, especially RET/PTC1 and PTC3 generated by the fusion of RET to the H4 or RFG genes, respectively, is frequently found in thyroid papillary carcinoma, particularly in childhood radiation-induced thyroid cancers." (PMID 12698188, 2003). "However, CNV analysis did not reveal RET amplification in any of the thyroid cancer samples." (PMID 41373459, 2025). "Moreover, in comparison to two other thyroid cancer cell lines with known constitutively activated AKT (being XTC.UC1 cells derived from Hürthle cell cancer and BHP 2-7 cells derived from PTC harboring RET/PTC1), baseline pAKT expression levels in JVE404 were ~94% lower." (PMID 33878728, 2021). "In addition to well-known BRAF, RAS, and RET mutations, NGS technology facilitated detection of new somatic alterations in thyroid cancer such as MITF, MDM2, JAK3, FLI1, IDH1 etc., all in which the significance of thyroid cancer has not been delineated yet." (PMID 27871285, 2016). "The 11 cancers with non-MTC diagnoses that had the common RET SSVs were 4 neuroendocrine cancers, 4 non-small cell lung carcinomas, 2 non-MTC thyroid cancers, and 1 melanoma." (PMID 38566816, 2024).
thyroid cancer (continued). "In the Cancer Genome Atlas study, RET and NTRK fusions were found in 6.8% and 1.2% cases, respectively, of mostly nonmetastatic thyroid cancers and thus were as frequent as in our study." (PMID 38630010, 2024). "Though three genes, i.e., RET, CDKN2A, and JAK2, are not enriched in a cancer related pathway with other detected genes, they are believed to have a close relationship with thyroid carcinoma." (PMID 37221474, 2023). "Recently, genetic and molecular analyses (such as tests for BRAF, RET/PTC, and RAS, among others) revealed diverse molecular characteristics of thyroid cancers, but most clinical trials applying RA did not analyze these factors." (PMID 29085335, 2017). "The insensitivity of RET-activated thyroid cancer cells to MEK inhibition has been previously demonstrated, as opposed to the high sensitivity of thyroid cancer cells expressing BRAFV600E." (PMID 23056499, 2012). "The cyclin D1 staining of stromal cells (not seen in WT and RET/PTC3 thyroids) is puzzling and not reported in human thyroid carcinomas." (PMID 18985036, 2008). "Importantly, the trial generated data in RET-rearranged, non-NSCLC, and non-thyroid cancer patients." (PMID 37627175, 2023). "Although these are not head-to-head comparisons, PRRT for thyroid cancer seems to have comparable ORRs to PRRT in NETs, and while the ORRs are better with TKIs or with selective RET inhibitors, PRRT seems to have a better safety profile compared to these systemic therapies." (PMID 35712243, 2022).
medullary thyroid carcinoma (415 papers, 2002 to 2026). "Our clinical case of metastatic medullary thyroid cancer, which is associated with RET mutations undergoing treatment with vandetanib, also suggests that vandetanib can decrease catecholamine levels." (PMID 40725174, 2025). "Accurate medullary thyroid cancer risk information is essential for effective risk-benefit discussions with individuals carrying incidentally identified pathogenic RET variants." (PMID 40577012, 2025). "For patients with advanced, radioiodine-refractory differentiated thyroid cancer (DTC) and medullary thyroid cancer (MTC) harboring specific genetic alterations such as RET mutations, conventional therapies yield suboptimal outcomes." (PMID 41278287, 2025). "Medullary thyroid carcinoma is a rare thyroid malignancy derived from parafollicular C cells that is frequently driven by activating mutations in the REarranged during Transfection (RET) proto-oncogene." (PMID 40638225, 2025). "Although relatively rare in the germline, pathogenic CNVs involving RET have been documented, particularly in the context of somatic alterations in medullary thyroid carcinoma (MTC)." (PMID 41465145, 2025). "The NM_020975.6:c.2410G>A; p.(Val804Met) RET (HGNC:9967) variant has reduced penetrance compared to other variants that contribute to RET-related medullary thyroid cancer and the Grpmax FAF is approximately four times the relevant BS1 threshold." (PMID 41000626, 2025). "RET mutations (both somatic and germline) are well described in the pathogenesis of medullary thyroid cancer (MTC)." (PMID 40332427, 2025). "Mutations in the RET gene can lead to various clinical manifestations, and the genetic profile of sporadic medullary thyroid carcinoma (MTC) is notably more intricate." (PMID 40791984, 2025). "Selpercatnib, approved for tumors with RET-activating mutations, has shown efficacy in medullary thyroid cancer and other solid tumors harboring RET fusions, as demonstrated in the Libretto trial." (PMID 40183077, 2025). "RET missense variants are highly prevalent in medullary thyroid carcinoma (MTC), occurring in more than 90% of cases, including both sporadic and hereditary forms." (PMID 41465145, 2025). "MEN 2 syndromes (caused by a mutation in the RET protooncogene), in particular, warrant evaluation of associated pathologies such as medullary thyroid carcinoma and hyperparathyroidism." (PMID 40709162, 2025). "RET mutations are common in medullary thyroid cancer, and the primary treatment is a TKI that blocks the activity of this receptor, with cabozantinib being the most widely used, however, without promising results." (PMID 40283927, 2025). "It lacks t(X;18) and RET mutations, differentiating it from synovial sarcoma and spindle cell variants of medullary thyroid carcinoma, respectively." (PMID 40099088, 2025). "This is the first report demonstrating the clinical efficacy of selpercatinib in a patient with medullary thyroid carcinoma harboring a RET A641R mutation, supporting the oncogenic potential of this rare variant." (PMID 40638225, 2025). "RET mutations are more prevalent in medullary thyroid cancer (MTC) than in papillary thyroid carcinoma (PTC)." (PMID 40363930, 2025). "It demonstrates that biomarkers are key for detecting aggressive anaplastic thyroid cancer, prognosticating outcomes for papillary thyroid cancer, and selecting precise treatments for medullary thyroid cancer, especially for cases with RET gene mutations." (PMID 39744583, 2025). "What are the medullary thyroid cancer risks for individuals with incidentally identified RET variants, and do they differ from individuals with RET variants ascertained clinically?" (PMID 40577012, 2025). "The findings of the present study are consistent with previous reports in the literature, which delineate distinct profiles of RET germline mutations in hereditary medullary thyroid carcinoma compared to cases that appear sporadic." (PMID 41514606, 2025).
medullary thyroid carcinoma (continued). "We report a case of a 59-year-old male with sporadic medullary thyroid carcinoma harboring a rare RET A641R mutation in the transmembrane domain." (PMID 40638225, 2025). "Of 75 moderate-risk RET carriers offered surgery, only 20 (26.7%) proceeded, with 12 showing histologically confirmed medullary thyroid cancer, predominantly stage 1 disease (10 of 12 [83.3%])." (PMID 40577012, 2025). "Multiple endocrine neoplasia type 2B (MEN2B) is a rare autosomal dominant disorder caused by RET proto-oncogene mutations, classically associated with medullary thyroid carcinoma (MTC), pheochromocytoma, and gastrointestinal ganglioneuromatosis." (PMID 41487748, 2025). "Genetic testing confirmed a RET M918T variant, and he subsequently underwent total thyroidectomy for medullary thyroid carcinoma." (PMID 41061409, 2025). "Among 169 RET pathogenic variant carriers in UK Biobank, only 2 (1.2% [95% CI, 0.1%-4.2%]) had medullary thyroid cancer at recruitment, 1 with a high-risk variant and 1 with a moderate-risk variant (eTables 5 and 6 in Supplement 1)." (PMID 40577012, 2025). "Medullary thyroid cancer penetrance was 25.0% (95% CI, 0.6%-80.5%) in high-risk RET variant carriers (1 of 4) and 12.3% (95% CI, 5.8%-22.1%) in moderate-risk carriers (9 of 73 carriers) (eTables 5 and 6 in Supplement 1)." (PMID 40577012, 2025). "Medullary thyroid carcinoma has seen advancements due to genetic research, particularly in identifying RET mutations, which help in selecting targeted treatments." (PMID 39744583, 2025). "The parathyroid involvement is described later across life span when compare to the medullary thyroid carcinoma and the familial cases harboring RET pathogenic variants should follow lifelong surveillance protocols of PTH and annual calcium assays." (PMID 39585007, 2024). "Medullary thyroid carcinoma is often associated with mutations in the RET proto-oncogene, which encodes a receptor tyrosine kinase involved in cell growth and differentiation." (PMID 39456563, 2024). "After emergency surgery, the patient was diagnosed with multiple endocrine neoplasia type 2B with medullary thyroid carcinoma, and a de novo variant of RET was confirmed." (PMID 38753051, 2024). "The presented patients were also identified with a RET gene variant linked to a significant risk of medullary thyroid carcinoma." (PMID 38802890, 2024). "MEN2A is highly penetrant, with a near 100% lifetime incidence of medullary thyroid cancer in individuals with a RET pathogenic variant." (PMID 39559597, 2024). "RET mutations have been identified in various cancer types, including medullary thyroid cancer, papillary thyroid cancer, and lung cancer—particularly non-small cell lung cancer, where RET rearrangements account for approximately 1%–2% of cases." (PMID 39872362, 2024). "Somatic RET mutations are more frequently associated with specific types of tumors, such as breast cancer and sporadic medullary thyroid carcinoma, while germline RET mutations are typically linked to particular syndromes, such as MEN2." (PMID 39194755, 2024). "Identifying the RET mutation allowed for targeted management and ongoing surveillance for associated risks, particularly the high likelihood of medullary thyroid cancer." (PMID 39559597, 2024). "Particular caution should be exercised to patients at increased risk or diagnosed with medullary thyroid cancer or mutations in the RET proto-oncogene and multiple endocrine neoplasia type 2 (MEN2), as well as with a family history of the disease." (PMID 39598383, 2024).